ENSG00000255439 (novel protein, VKORC1 and PRSS53 readthrough)
Gene: Protein-coding gene on chromosome 16 (31,083,439 to 31,094,956, reverse strand). Ensembl gene ENSG00000255439.
Genetic constraint (gnomAD): Loss-of-function variants: 20 observed, 23.16 expected, observed/expected ratio (o/e) 0.86, 90% interval 0.61 to 1.25. Missense variants: 241 observed, 222.16 expected, observed/expected ratio (o/e) 1.08, 90% interval 0.98 to 1.21. Synonymous variants: 99 observed, 88.46 expected, observed/expected ratio (o/e) 1.12, 90% interval 0.95 to 1.32.